KCNQ1OT1 (KCNQ1 opposite strand/antisense transcript 1)
Diseases named in the same sentence as KCNQ1OT1 in open-access papers (continued):
Sharing a sentence is not in itself a finding about the gene and the disease.
tumor (continued). "Besides, KCNQ1OT1 knockdown inhibited CRC tumor growth through the miR-329-3p/CTNND1 axis in vivo." (PMID 32760218, 2020). "Furthermore, the effects of KCNQ1OT1 knockdown on tumor growth were further revealed in vivo." (PMID 32760218, 2020). "Moreover, the knockdown of Kcnq1ot1 exerts a tumor-suppressive effect in some of these cancers." (PMID 30651140, 2019). "Additionally, HOXA13 and KCNQ1OT1 were upregulated in HCC tumor tissues." (PMID 26136615, 2015). "KCNQ1OT1 behaves as a molecular sponge for miR-15a, increasing PD-L1 expression and inhibiting CD8+ T cell cytotoxicity, leading to immune evasion and tumor progression." (PMID 41154428, 2025). "Among these features, five were clinical: pathological stage, new tumor event, number of lymph nodes, weight, age, and chemotherapy; and two were biological features: E2F8 and KCNQ1OT1." (PMID 41401030, 2025). "Expression analysis of the excised tumor tissues revealed that compared to the sh-NC group, the sh-RBM15 group exhibited decreased expression of RBM15, KDM5B, and KCNQ1OT1, and increased expression of FER1L4 (p < 0.01)." (PMID 39039611, 2024). "qRT‐PCR verified that HOXA9 was highly expressed in LSCC tissues compared with non‐tumour tissues in 86 pairs of LSCC sample cohort, and its expression was positively correlated with the expression level of KCNQ1OT1." (PMID 34850551, 2022). "miR-140-5p, as the downstream target gene of KCNQ1OT1, targets and regulates the downstream RAB11A, and it is involved in the proliferation and tumor progression of PA." (PMID 35432529, 2022). "Then, we further expanded the LSCC sample to detect KCNQ1OT1 methylation level in 86 pairs of LSCC and non‐tumour tissues." (PMID 34850551, 2022). "Based on TCGA database, we found that KCNQ1OT1 was overexpression in HNSCC and related to tumour grade." (PMID 34850551, 2022). "It is further confirmed that there is a direct binding site between KCNQ1OT1 and HOXA9, and rescue experiments demonstrate that ALKBH5‐KCNQ1OT1‐HOXA9 axis affects tumour proliferation, invasion and metastasis." (PMID 34850551, 2022). "The long non-coding RNA gene KCNQ1 overlapping transcript 1 (lncRNA KCNQ1OT1) sponged miR-15a to upregulate the expression of PD-L1, thus inhibiting the cytotoxicity of CD8+ T cells and promoting tumor evasion." (PMID 34830196, 2021). "Knockdown of KCNQ1OT1 also reduced CAL27 and SCC9 cisplatin-resistant cell proliferation as well as tumor growth and weight in vivo via the miR-124-3p/TRIM14 axis." (PMID 34827600, 2021). "A series of cellular behaviors experiments revealed that overexpression of KCNQ1OT1 or XIST greatly aggravated CRC cell proliferation in vitro and tumor growth in vivo, acting as oncogene in CRC." (PMID 34521445, 2021). "Knocking down KCNQ1OT1 lowered PD-L1 expression and inhibited the viability, migration, invasion, and EMT of tumor cells, favoring their apoptosis; moreover, it enhanced the cytotoxicity and proliferation of CD8+ T-cells, reducing their apoptosis." (PMID 34830196, 2021). "Herein, RT-qPCR was utilized for determining the levels of KCNQ1OT1, miR-296-5p and HYOU1 in clinical tumor tissue specimens and CC cell lines." (PMID 34704918, 2021). "Elevated KCNQ1OT1 and HYOU1 as well as reduced miR-296-5p were observed in clinical tumor tissue specimens and CC cell lines." (PMID 34704918, 2021). "KCNQ1OT1 was shown to regulate PD-L1 expression by sponging miR-15a in PCa, resulting in the inhibition of cytotoxicity of CD8+ T cells and promotion of tumor evasion." (PMID 34827600, 2021). "Functionally, knocking down KCNQ1OT1 lowered PD-L1 expression, inhibited the viability, migration, invasion and EMT, promoted the apoptosis of tumor cells, and enhanced the cytotoxicity and proliferation, while reduced the apoptosis of CD8+ T cells." (PMID 32821247, 2020).
tumor (continued). "In this study, we showed for the first time that lncRNA KCNQ1OT1 sponged miR-15a to up-regulate PD-L1 expression, resulted in inhibiting the cytotoxicity of CD8+ T cells and promoting tumor evasion." (PMID 32821247, 2020). "Indeed, the chromosome alterations affecting the H19, KCNQ1OT1, PLAGL1 and GNAS DMRs also affected one or more WT driver genes in all analyzed cases, and the chromosome variants affecting the MEST, GRB10 and MEG3 DMRs also affected tumor driver genes in at least 83% of cases." (PMID 33217932, 2020). "Consistent with previous study, the level of KCNQ1OT1 in NSCLC tissues and cell lines was dramatically higher than that in non-tumor tissues and cells." (PMID 32377169, 2020). "In accordance with previous reports in several human cancers, a high level of KCNQ1OT1 was found in our LUAD cohort, which correlated with large tumor size, an advanced clinical stage and shorter survival of patients." (PMID 33082306, 2020). "To ensure the EPIC array data truly reflects the methylation profile at imprinted DMRs, we performed pyrosequencing for the H19, KCNQ1OT1, and FAM50B regions which confirmed that the tumour sample is 22–24% less methylated than the corresponding placenta." (PMID 31357948, 2019). "Our experimental results and statistical analyses determined that lncRNA KCNQ1OT1 and PPP1R1B mRNA were aberrantly up‐regulated in MTX‐resistant CRC tumour tissues and cells." (PMID 30997746, 2019). "LncRNAs KCNQ1OT1 and TUB-AS1 were lower while TEX41 was higher in tumours than those in normal tissues (P < 0.001)." (PMID 31523056, 2019). "One week after tumor cell inoculation, the nude mice bearing xenografts of CAL27 cells with control shRNA or those with shRNA against KCQ1OT1 (CAL27-sh-KCNQ1OT1) were randomly selected for treatment with either cisplatin or PBS." (PMID 29970910, 2018). "lncRNAs such as DIO3OS, EMX2OS, KCNQ1DN, KCNQ1OT1, LOH12CR2, and RFPL1S have been shown to associate with a negative gene signature, which links lncRNA to tumor suppression mechanisms." (PMID 41300873, 2025). "Our results suggest that silencing KCNQ1OT1 in HCT116 and SW480 cells could suppress tumor progression." (PMID 38361755, 2024). "Thus, IC2 methylation and KCNQ1OT1 imprinting were similarly relaxed in the neoplastic and peri-neoplastic tissues and KCNQ1 was increased in the tumor of our patient." (PMID 37046605, 2023). "Additionally, the lncRNA KCNQ1OT1 regulates the imprinted expression of the KCNQ1 and CDKN1C genes, both showing tumor suppressor activity in several tumors, including CRC." (PMID 37046605, 2023). "Our study revealed another lncRNA KCNQ1OT1/miR-328-3p/IL1B regulatory axis in LUSC, which may also play a vital function in the tumor progression." (PMID 35692583, 2022). "Next, we verified KCNQ1OT1 upregulation in 86 pairs of LSCC and non‐tumour tissues by qRT‐PCR." (PMID 34850551, 2022). "Compared with the negative control group, the tumour volume and weight of KCNQ1OT1 knockdown group were significantly reduced." (PMID 34850551, 2022). "As a result, only miR-30a-5p had the most significant difference, and after verification by TCGA database, it was found that miR-30a-5p and KCNQ1OT1 had a negative correlation in tumor patients." (PMID 34350172, 2021). "In PC cell lines, KCNQ1OT1 sponged miR-15a, suppressing the miR-15a-mediated inhibition of PD-L1, thus leading to PD-L1 upregulation, the inhibition of CD8+ T-cells cytotoxicity, and the promotion of tumor evasion." (PMID 34830196, 2021). "The mechanism responsible for KCNQ1OT1 upregulation is still unknown, while the KCNQ1OT1/miR-15a/PD-L1 axis apparently promotes RAS/ERK signaling activation, inducing tumor immune evasion." (PMID 34830196, 2021). "However, its role as an intermediate pathway between KCNQ1OT1 and USP22 to regulate tumor immune escape is the first report and verification in this study." (PMID 34350172, 2021).
tumor (continued). "Downregulation of KCNQ1OT1 inhibits SCLC cell proliferation, migration, and invasion, induces apoptosis, and suppresses tumor growth and chemoresistance via TGF-β-mediated EMT signaling and the Janus kinase (JAK)/signal transducer and activator of transcription 3 (STAT3) signaling pathway." (PMID 34827600, 2021). "In a xenograft mouse model, knockdown of KCNQ1OT1 inhibited CRC cell growth and decreased tumor volume, while overexpression of KCNQ1OT1 induced protective autophagy and chemoresistance to oxaliplatin (OXA) by sponging miR-34a and upregulating autophagy-related 4B (Atg4B)." (PMID 34827600, 2021). "In our study, based on the ceRNA hypothesis, tumor-promoting genes, including KCNQ1OT1, JARID2, CDK6, DNMT3A, and TET1, competitively bound the tumor suppressor gene hsa-29c-3p." (PMID 32127798, 2020). "Similarly, knockdown of KCNQ1OT1 also promoted the expression of miR-34c-5p and inhibited the expression of ALDOA in tumor tissues from a subcutaneous xenograft mouse model." (PMID 32332718, 2020). "Furthermore, qRT-PCR results suggested that the levels of KCNQ1OT1 and CTNND1 were declined in tumor tissues from the sh-KCNQ1OT1 group versus the sh-con group, while the miR-329-3p level was increased." (PMID 32760218, 2020). "Here, KCNQ1OT1 levels were 4-fold higher in tumor tissues compared with that in the adjacent noncancerous, which were defined as the high expression group." (PMID 32564010, 2020). "As compared with paired non-tumor tissues, KCNQ1OT1 was significantly increased in pretherapy LUAD tissues with a mean value of 2.11, which was used to divide LUAD samples into high and low KCNQ1OT1 groups." (PMID 33082306, 2020). "To examine the potential crosstalk among KCNQ1OT1, miR-15a, PD-L1, and CD8+ cytotoxic T cells in PC, we compared the expression levels of these molecules between 30 pairs of PC tissues and matching para-tumor normal tissues." (PMID 32821247, 2020). "The xenograft tumor volume was measured after 4 weeks of injection, and the tumor volume was smaller in sh-KCNQ1OT1 group compared with group injected with sh-negative control (NC) group." (PMID 31827399, 2019). "H19, KCNQ1OT1, and MEG3 are also known imprinted genes that function as tumor suppressors." (PMID 30732658, 2019). "LncRNA KCNQ1OT1 and PPP1R1B mRNA were overexpressed in MTX‐resistant CRC tumour cells." (PMID 30997746, 2019). "Additionally, the tumour mass of the nude mice in the HT29/MTX + KCNQ1OT1 group was greater than that of the HT29 group and the HT29/MTX group, whereas the tumour mass in the HT29/MTX + si‐KCNQ1OT1 group was relatively smaller than that of the HT29/MTX group." (PMID 30997746, 2019). "In this study, we revealed the importance of the KCNQ1OT1/miR-378a-3p/RBMS1 axis as a ceRNA regulation network for GC prognosis by analyzing high-throughput sequencing datasets and exploring a multigene prognostic model for tumor-related mortality estimation in GC patients." (PMID 35910231, 2022). "Furthermore, the KCNQ1OT1 knockdown group and the negative control group were implanted subcutaneously of nude mice, respectively, to construct the xenograft tumour model." (PMID 34850551, 2022). "However, the apoptosis detection of SW1463 cocultured with T cells found that although overexpression of KCNQ1OT1 reduced tumor cell apoptosis to a certain extent, there was no statistical difference in this apoptosis." (PMID 34350172, 2021). "Prior evidence suggests that the downregulation of KCNQ1OT1 expression in HCT116 cells may suppress cell proliferation, decrease the proportion of cells in the G2/M phase in vitro, as well as significantly reduce tumor size and cellular vitality in ectopic xenografts in nude mice." (PMID 38361755, 2024). "However, the role of lncRNA KCNQ1OT1 in tumor glycolysis has not been demonstrated." (PMID 32564010, 2020).
tumor (continued). "However, it is important to note that IC2 methylation and KCNQ1OT1 imprinting were similarly relaxed in the neoplastic and peri-neoplastic tissues, and KCNQ1 and CDKN1C were not repressed in the tumor with respect to normal tissue in our patient." (PMID 37046605, 2023). "Another study revealed that KCNQ1OT1 was a prognostic biomarker in non-SCLC and could accelerate tumor progression by the regulation of miR-204-5p/ATG3 axis." (PMID 35692583, 2022).
cancer (70 papers, 2009 to 2025). A tumor composed of atypical neoplastic, often pleomorphic cells that invade other tissues. "KCNQ1OT1/Kcnq1ot1, an lncRNA transcribed from the opposite strand of KCNQ1 within the CDKN1C/KCNQ1OT1 cluster, has been implicated as a critical factor in cancer development and progression." (PMID 39201613, 2024). "The aberrant expression of KCNQ1OT1 in cancer patients is associated with poor prognosis and decreased survival." (PMID 34827600, 2021). "We observed from the expression correlation heatmap that CTNNB1 was significantly associated with lncRNA KCNQ1OT1 across cancers." (PMID 33994860, 2021). "The results showed that KCNQ1OT1 was upregulated in the cancer tissues, and its high expression is associated with poor prognostic outcome." (PMID 34350172, 2021). "We also discuss the role of KCNQ1OT1 as a promising diagnostic biomarker and a novel therapeutic target in human cancers." (PMID 34827600, 2021). "A previous report indicated that KCNQ1OT1 was associated with cell proliferation, apoptosis, prognosis, invasion, and metastasis in various cancers." (PMID 34917682, 2021). "In addition, KCNQ1OT1 can upregulate Ezrin, a protein differentially expressed in aggressive cancer types and associated with poor survival, and promote cisplatin resistance of CAL27-res and SCC9-res cells through binding with miR-211-5p." (PMID 34827600, 2021). "KCNQ1OT1 has been reported to associated with progression and metastasis of various cancers." (PMID 31164794, 2019). "Therefore, aberration of the extent of the KCNQ1OT1 lncRNA-coated territory that is caused by an excess of nuclear β-catenin may play a significant role in the process of cancer development." (PMID 26868975, 2016). "Although our two BWS patients, who showed hypomethylation of KCNQ1OT1 (KCNQ-CR), have a low cancer risk, regular follow-up is recommended." (PMID 40730975, 2025). "KCNQ1OT1 plays a vital role in the development and progression of several types of cancer, including HCC." (PMID 40699747, 2025). "These contrasting findings highlight KCNQ1OT1/Kcnq1ot1 as a potential target for cancer therapeutics." (PMID 39201613, 2024). "Previous studies have indicated that lncRNA KCNQ1OT1 participates in regulating cell proliferation and cell cycle, which contributes to the cancer phenotype." (PMID 38361755, 2024). "Our findings contrast with previous studies on KCNQ1OT1/Kcnq1ot1 in various cancers, highlighting its complex role in different pathological contexts." (PMID 39201613, 2024). "While previous studies consistently reported KCNQ1OT1/Kcnq1ot1 overexpression in diverse cancers, our results demonstrate decreases in its expression." (PMID 39201613, 2024). "In particular, KCNQ1OT1 has been widely reported to be a cancer promoter in various types of tumors, such as non-small cell lung carcinoma, colorectal cancer, tongue cancer, and breast cancer." (PMID 38835012, 2024). "KCNQ1 opposite strand/antisense transcript 1 (KCNQ1OT1) is a novel lncRNA that plays a vital role in cancer progression." (PMID 36605618, 2023). "ALKBH5 is also overexpressed within LSCC and influences the m6A-methylated level of KCNQ1OT1 through modulating specific positions upon KCNQ1OT1, modulating cancer cell proliferation, invasion and metastasis." (PMID 37816718, 2023). "In human HEK293T cancer cells, KCNQ1OT1 expression influences the abundance of H3K9me3 foci in the nucleus, and deletion studies show that this effect is conferred by a repeat-rich region at the 3′ part of the lncRNA." (PMID 37686455, 2023). "By performing CHIRP-seq, an RNA hybridisation assay that precipitates the genomic chromatin sites bound to the bait RNA, the authors identified evolutionarily young transposons as the main targets of the KCNQ1OT1 RNA in cancer cells." (PMID 37686455, 2023). "NEAT1 and KCNQ1OT1 have been reported to be upregulated in a variety of cancers and promote tumorigenesis by altering the expression levels of sponged miRNAs." (PMID 36237545, 2022).